PLET1 (placenta expressed transcript 1)
Description:
Modulates leading keratinocyte migration and cellular adhesion to matrix proteins during a wound-healing response and promotes wound repair. May play a role during trichilemmal differentiation of the hair follicle (By similarity).
Synonyms: C11orf34
Tractability: Antibody: its Gene Ontology location is reachable by antibodies, with high confidence; UniProt places it where antibodies can reach, with medium confidence; UniProt predicts a signal peptide or a membrane-spanning region.
Gene: Protein-coding gene on chromosome 11 (112,248,153 to 112,260,860, reverse strand). Ensembl gene ENSG00000188771.
Subcellular location: Apical cell membrane
Pathways (Reactome):
Metabolism of proteins: Post-translational modification: synthesis of GPI-anchored proteins
Gene Ontology:
Biological process: negative regulation of cell-matrix adhesion; positive regulation of cell migration; wound healing, spreading of epidermal cells
Cellular component: apical plasma membrane; external side of plasma membrane; extracellular region; plasma membrane
Genetic constraint (gnomAD): Loss-of-function variants: 17 observed, 17.64 expected, observed/expected ratio (o/e) 0.96, 90% interval 0.66 to 1.44. The upper end of that interval is the gene's LOEUF score, 1.44, which puts it in group 5 of 6, group 1 being the genes least tolerant of losing a copy. Missense variants: 251 observed, 251.4 expected, observed/expected ratio (o/e) 1, 90% interval 0.9 to 1.11. Synonymous variants: 89 observed, 95.07 expected, observed/expected ratio (o/e) 0.94, 90% interval 0.79 to 1.12.
Homologues: Orthologues: chimpanzee PLET1 (99% identical), macaque PLET1 (82% identical), dog PLET1 (36% identical), pig PLET1 (36% identical), mouse Plet1 (29% identical), rat Plet1 (29% identical).
Diseases named in the same sentence as PLET1 in open-access papers:
PLET1 is named in the same sentence as 9 diseases in open-access papers, as found by Europe PMC text mining. Sharing a sentence is not in itself a finding about the gene and the disease. The quoted sentences say what the papers report.
colon cancer (1 paper, 2021). "In the AOM/DSS colon cancer model, PLET1 has been shown to be an IL-17A-induced protein." (PMID 34868026, 2021).
influenza (1 paper, 2024). An acute viral infection of the respiratory tract, occurring in isolated cases, in epidemics, or in pandemics; it is caused by serologically different strains of viruses (influenzaviruses) designated A, B, and C, has a 3-day incubation period, and usually lasts for 3 to 10 days. "Independently of the source; it has to be highlighted that local administration of recombinant Plet1 reproduced the epithelial-protective and -regenerative effects driven by Plet1+ macrophage populations, and rescued 85% of mice from fatal influenza." (PMID 38167746, 2024).
viral pneumonia (1 paper, 2024). Inflammation of the lung parenchyma that is caused by a viral infection. "Finally, intraalveolar administration of recombinant Plet1 rescued mice from fatal viral pneumonia, highlighting its potential as a therapeutic to combat severe inflammatory lung injury in viral pneumonia." (PMID 38167746, 2024). "Here, we reveal that during the resolution phase of viral pneumonia a transitional subpopulation of BMDM and the re-emerging TR-AM pool constitute key components of epithelial stem/progenitor cell niches and contribute to lung regeneration after injury through the expression of Plet1." (PMID 38167746, 2024).
tumor (3 papers, 2015 to 2022). "They analyzed Plet 1-deficient mice in the AOM/DSS model and found reduced tumor numbers and reduced expression of proliferation marker Ki67, suggesting IL-17A-induced Plet1 expression contributes to colon tumorigenesis and cell proliferation." (PMID 36135048, 2022). "Robust expression of Lrig1 and Plet1 was also detected by immunofluorescence staining in K15ΔNLef1 tumours." (PMID 25608467, 2015). "Plet1 was predominantly detected in undifferentiated and adipophilin− tumour cells localized to ductal structures facing the surface of the skin (arrows)." (PMID 25608467, 2015). "In contrast, expression of Plet1 and Lrig1, markers for progenitors and SCs of the upper IR and JZ, respectively, were strongly expressed within SC-driven tumours." (PMID 25608467, 2015).
PLET1 also shares sentences with these, for which no sentence is quoted: infection (2 papers); neurological disease (1); thymic atrophy (1); Thyroid adenoma (1); viral infection (1).